GAPDH (glyceraldehyde-3-phosphate dehydrogenase)
Diseases named in the same sentence as GAPDH in open-access papers (continued):
Sharing a sentence is not in itself a finding about the gene and the disease.
Obesity (17 papers, 2006 to 2026). Accumulation of substantial excess body fat. "Altered GAPDH expression in human muscle has been associated with IR and a tendency towards a higher lipogenic gene expression, which are associated with obesity phenotype." (PMID 38703299, 2024). "In contrast, a low abundance of GAPDH was found in platelets of individuals with obesity compared to lean patients; however, limitations of the study, including number and gender of individuals analysed should be considered." (PMID 38703299, 2024). "It was reported an increased protein abundance of GAPDH in SKM of individuals with obesity compared to lean patients." (PMID 38703299, 2024). "The reduced GAPDH acetylation was also observed in the liver of obesity and type 2 diabetes mouse models, and key lysine residues in GAPDH contribute to the regulation of glucose tolerance and sensitivity to glucagon and insulin." (PMID 33043000, 2020). "UBC was the least stable gene in expression in all six types of tissues during the development of obesity, followed by GAPDH, ACTB, and 18S, which have been commonly used in the adipose tissue and hepatic tissue." (PMID 33330591, 2020). "In studies on obesity and other diseases, GAPDH, β-actin, or β-tubulin has been used extensively as housekeeping protein in determination of target protein expression." (PMID 33330591, 2020). "Our study first identified that AHR transcripts (relative to GAPDH) were notably increased in the PBMCs from both obesity and T2D patients compared with lean healthy subjects with a normal BMI." (PMID 32849564, 2020). "On the other hand, GAPDH transcript levels were higher in LHB vs. PHB mice; this gene and its activity were linked to obesity in rat models." (PMID 30071904, 2018). "For example, Aldolase A was 3.3 times overexpressed in obesity/insulin resistance and GAPDH 4 times higher." (PMID 17178004, 2006). "In addition, significant increased abundance of glycolytic enzymes, including GAPDH, were found in women with obesity or morbid obesity, relative to lean control subjects." (PMID 38703299, 2024). "Furthermore, Catalan and his colleagues showed that GAPDH is a less appropriate reference gene in human omental and subcutaneous adipose tissue from obesity and type 2 diabetes patients, because of the variational expression." (PMID 27338366, 2016). "However, the GAPDH expression were significantly downregulated by FA mixtures in both basal and 8-Br-cAMP-stimulated states, indicating long-term exposure of FAs induced strong apoptosis of primary Leydig cell even under rational concentration during obesity." (PMID 34131222, 2021). "GAPDH over-expression may be attributed to compensate for the progressive decrease in muscle mitochondrial function due to FFA induced ROS and contribute to loss of glucose and lipid homeostasis and eventually obesity and T2D." (PMID 19997558, 2009). "In conclusion, CYCA, GAPDH and RPL27 were identified as the most stable reference genes common to Genorm, Normfinder and Bestkeeper algorithms for studies involving human EAT, not only in context of obesity but also under a variety of other conditions." (PMID 22511915, 2012). "From the information gathered regarding their individual functions, we propose that under conditions of stress and obesity, the interactions between SUMO4 and GAPDH play a role in regulating insulin and EGFR signalling to increase vascular complications in diabetic subjects." (PMID 19997558, 2009). "Analysis of Nppa, Nppb, Pln, and GFPdgn may have been more suited for normalization with 36B4 rather than GAPDH as GAPDH has been shown to change during obesity and metabolic syndrome." (PMID 37362441, 2023). "During the past decades, β-actin (ACTB), glyceraldehyde-3-phosphate dehydrogenase (GAPDH), 18S ribosomal RNA (18S), ribosomal protein large P0 (RPLP0), and TATA box-binding protein (TBP) have been used extensively as reference genes in physiological status and diseases including obesity." (PMID 33330591, 2020).
cervical carcinoma (15 papers, 2008 to 2024). A carcinoma arising from either the exocervical squamous epithelium or the endocervical glandular epithelium. "Likewise, GAPDH inhibition caused by antisense oligonucleotides in human cervical carcinoma affects cell proliferation and induces apoptosis." (PMID 25859407, 2015). "According to the median ratio of relative HOTAIR expression (HOTAIR/GAPDH ratio of 0.975) in tumor tissues, we divided the 91 patients with cervical cancer into a high HOTAIR expression group (n = 46) and a low expression group (n = 45)." (PMID 27467165, 2016). "The average relative expression (compared with GAPDH) of KLF4 was 12.36±2.24 in normal cervix but 1.642±0.31 in cervical carcinoma." (PMID 24551169, 2014). "A study using anti-sense oligodeoxynucleotide of the GAPDH gene inhibited cell proliferation and induced apoptosis in human cervical cancer cell lines." (PMID 21073742, 2010). "Remarkably, antisense oligodeoxynucleotides targeting GAPDH inhibit cell proliferation and induce apoptosis in cervical carcinoma cells." (PMID 19014639, 2008). "Thus far, auto-antibodies recognizing two different antigens have been identified in cervical cancer—one is the tetra saccharide CA19-9, which strongly increases in patients with more advanced cervical cancer, and one is GAPDH." (PMID 33672007, 2021). "The authors showed that lower anti-GAPDH IgG levels could discriminate between normal cells and more progressive stages of cervical lesions that often lead to cervical cancer (e.g., normal vs. cervical intraepithelial neoplasia (CIN) II and III)." (PMID 33672007, 2021). "In cervical cancer, GAPDH interacts with Rab2 and participates in membrane recruitment." (PMID 25859407, 2015). "In addition, high expression of glyceraldehyde-3-phosphate dehydrogenase (GAPDH) protein in HeLa cervical cancer cells can recover mitochondrial outer membrane, promote cell division and proliferation after induction of apoptosis in the absence of caspase, and eliminate MOMP during anastasis." (PMID 35659306, 2022). "For molecular screening, we selected GAPDH as the biomarker for cervical precursor lesions and HNRNPA1 as the biomarker for cervical cancer -chosen from the three previously identified options based on antibody availability- to be detected in sera." (PMID 39610929, 2024). "Following normalization to GAPDH expression in the tissues, TXNDC5 expression was significantly increased in cervical cancer tissues compared with uterine myoma tissues (p = 0.0003)." (PMID 29207620, 2017). "One cervix cancer cell line, C33A, did not yield RT-PCR products with any of the three primer pairs, although it did give the expected product for in the GAPDH control amplification." (PMID 24204631, 2013).
osteosarcoma (15 papers, 2009 to 2025). A usually aggressive malignant bone-forming mesenchymal neoplasm, predominantly affecting adolescents and young adults. "Although GAPDH mRNA expression remained largely unchanged, Western blot analysis at the protein level revealed suppression of GAPDH in osteosarcoma (O-P2), liposarcoma (L-P5), and rhabdomyosarcoma (Rm-P6) CSC samples." (PMID 41300532, 2025). "To confirm the cellular localization of circ‐0000190, we isolated osteosarcoma cells into cytoplasmic and nuclear fractions, with GAPDH and U6 as controls, respectively." (PMID 31923350, 2020). "To confirm the cellular localization of NEAT1, we isolated osteosarcoma cells into cytoplasmic and nuclear fractions, with GAPDH and U6 as controls, respectively." (PMID 31044561, 2019). "The expression of DANCR in collected 95 cases of osteosarcoma tissues and matched para-tumor tissues were determined by applying of quantitative real-time PCR (qRT-PCR) as normalizing to GAPDH." (PMID 29753317, 2018). "We have targeted GAPDH in osteosarcoma U2-OS cells for HiBiT insertion and observed similar effects." (PMID 30271937, 2018). "Notably, the expression of the control gene GAPDH was highly consistent among all clones whereas the expression of the other used control gene, L32, was consistent among the osteosarcoma and carcinoma clones but was less consistent among the spindle cell clones." (PMID 19771160, 2009). "Subsequently, human osteosarcoma MG-63 cells were divided into control, COL5A2-enhanced, and COL5A2-knockdown groups and the different expression levels of COL5A2 in MG-63 cells were verified using qRT-PCR with GAPDH as the control gene." (PMID 35280775, 2022). "As expected, the RNA expression of EBLN3P was higher and that of miR-224-5p was lower in osteosarcoma tissues compared with non-neoplastic bone tissues (normalized to GAPDH)." (PMID 33479458, 2021). "RT-qPCR was used to detect MALAT1 expression in 64 primary osteosarcoma tissues and paired adjacent noncancerous tissues, normalized to GAPDH." (PMID 29290978, 2017). "Western blot analysis revealed that NP does not affect the levels of eIF4E and control protein GAPDH, though it does modulate 4E-BP1 protein levels in osteosarcoma cells at the level of phosphorylation." (PMID 30286779, 2018).
non-small cell lung carcinoma (14 papers, 2008 to 2025). A group of at least three distinct histological types of lung cancer, including non-small cell squamous cell carcinoma, adenocarcinoma, and large cell carcinoma. "Up-regulation of CCNB1 is consistently associated with high-expressions of GAPDH in non-small-cell lung cancer." (PMID 32635458, 2020). "In a study where median GAPDH expression in non-small cell lung cancer was slightly less than in control healthy tissue, a substantial median fold change (>2.4)—or lack of stability—of expression levels between healthy and tumor tissue was noted." (PMID 40943534, 2025). "Most of the hub genes in the network like GAPDH, IL6, CDK1, PTEN, etc. are either associated with non-small cell lung cancer itself or other forms of cancers." (PMID 35330393, 2022). "But, GAPDH is reported to be up-regulated in some cancers, e.g., by a factor of 3 to 6 in non small cell lung cancer compared to normal lung tissue." (PMID 20731868, 2010). "However, the transcriptional levels of GAPDH may be highly up-regulated in some cancers, including non-small cell lung cancers (NSCLC)." (PMID 23620736, 2013). "SPP1 with glycolysis genes (GAPDH, ENO1, LDHA, ALDOA, and TPI1) was also expressed in TAMs in non-small cell lung cancer (NSCLC)." (PMID 38347955, 2023). "For example, transfection of non-small cell lung cancer (NSCLC) cell lines with miR-31-5p mimics was shown to lead to an increase in cell proliferation, glucose uptake and the production of GLUT 1, GAPDH and LDHA proteins." (PMID 35205318, 2022). "This is a non-coding RNA which was identified in 2003 in non-small cell lung cancer, was shown to be highly expressed (relative to GAPDH) in lung, pancreas and prostate, but not in other tissues including muscle, skin, stomach, bone marrow, saliva, thyroid and adrenal glands, uterus and fetal liver." (PMID 20805891, 2010). "However, different studies had shown the variability of GAPDH expression in non-small cell lung cancer, suggesting that GAPDH may not be the most suitable housekeeping gene to investigate gene expression of lung cells." (PMID 25969744, 2012).
schizophrenia (13 papers, 2007 to 2024). A major psychotic disorder characterized by abnormalities in the perception or expression of reality. "We then compared levels of mRNA across diagnoses in BA 8 and BA 44 excluding data from cases with RIN < 5; analyses which showed the loss of the strong trend to higher levels of GAPDH in BA 8 from subjects with schizophrenia that was present using data from the whole cohort." (PMID 27206773, 2016). "A significant positive relationship between the levels of anti-GAPDH antibodies in the serum and detrimental cognitive and mood conditions (such as schizophrenia and major depression) in patients with SLE has been reported." (PMID 38398500, 2024). "Anti-GAPDH antibodies have also been detected in patients with schizophrenia and major depression, and administration of these immunoglobulins to mice leads to cognitive and behavioral alterations." (PMID 36816132, 2023). "Proteomics analysis of post mortem brains of patients with schizophrenia showed alterations in the levels of energy metabolism-associated proteins, such as aldolase C (ALDOC), enolase 2 (ENO2), and glyceraldehyde-3-phosphate dehydrogenase (GAPDH)." (PMID 30890939, 2019). "Our data are partly supported by another study that reported higher levels of GAPDH mRNA in the cortex of subjects with schizophrenia." (PMID 27206773, 2016). "There were no significant changes in mRNA levels between diagnoses in BA 8 or 44; there was a strong trend to higher levels of GAPDH mRNA in BA 9 from subjects with schizophrenia." (PMID 27206773, 2016). "Patients with schizophrenia showed significantly lower ADAR2 expressions in both Glyceraldehyde 3-phosphate dehydrogenase (GAPDH)- and CFL1-normalized data (P < 0.05)." (PMID 24443933, 2014). "GAPDH antibodies have been found in at least 50% of NPSLE patients with schizophrenia and major depression and may be a future potential biomarker of NPSLE." (PMID 38398500, 2024). "In glycolysis, the gene ENO1 showed a discordant expression pattern between the two groups (i.e., ENO1 was upregulated in schizophrenia and downregulated in ketosis), whereas the genes GAPDH and PFKP showed a concordant expression pattern, being downregulated in both states." (PMID 39125835, 2024). "In addition, none of the studied histone PTMs was found to be different between schizophrenia and control subjects at promoter region of reference gene GAPDH." (PMID 34930904, 2021). "Notably, GAPDH protein has been reported as decreased in the cortex from subjects with schizophrenia, suggesting the increase in gene expression may be an attempt to compensate for low protein levels." (PMID 27206773, 2016). "In BA 9 there were higher levels of GAPDH (p = 0.03) and SNCA (p = 0.04) in the cortex of subjects with schizophrenia; there was also a trend (p = 0.08) toward higher levels of PPIA mRNA." (PMID 27206773, 2016). "To address this issue we measured levels of mRNA for six potential reference genes (GAPDH, PPIA, SNCA, NOL9, TFB1M and SKP1) in three cortical regions (Brodmann’s areas (BA) 8, 9 and 44) from 30 subjects with schizophrenia and 30 age and sex matched controls." (PMID 27206773, 2016). "GAPDH and TPI, identified in this study to be differentially regulated in ASD, have been reported to be differentially expressed in brains of schizophrenia patients." (PMID 24512814, 2014). "Turning to our data across diagnoses, our analyses using the geometric mean of levels of mRNA of three region specific reference genes identified using our internal approach showed that levels of GAPDH and SNCA mRNA were higher in BA 9 from subjects with schizophrenia compared to controls." (PMID 27206773, 2016). "The glycolytic enzyme GAPDH is a redox-sensitive key enzyme of glycolysis and together with its immediate glycolytic neighbor TPI1 has previously been reported to be differentially regulated in schizophrenia." (PMID 24512814, 2014).
schizophrenia (continued). "These analyses showed i) a strong trend to higher levels of GAPDH mRNA (p = 0.06) in BA 8, ii) higher levels of GAPDH (p = 0.02) and SNCA (p = 0.04) mRNA in BA 9 and iii) lower levels of PPIA (p = 0.04), SNCA (p = 0.02) and NOL9 (p = 0.04) in BA 44 from subjects with schizophrenia." (PMID 27206773, 2016). "In the DPFC, DAO mRNA normalized to r18s was unchanged in schizophrenia (Mann–Whitney U-test, P = 0.33) as was DAO mRNA normalized to GAPDH (data not shown)." (PMID 17880399, 2007).
diabetic retinopathy (12 papers, 2007 to 2025). "Hyperglycemia, which remains an important factor in post-diabetes retinopathy, leads to a significant increase of nitrosylated GAPDH in retinal cells, which causes the intranuclear translocation of the enzyme and induction of apoptosis." (PMID 32370188, 2020). "GAPDH is a key player in the mechanisms underlying the onset and progression of diabetic retinopathy, suggesting that active compounds targeting GAPDH could hold significant therapeutic potential." (PMID 40699728, 2025). "In an in vivo study, GAPDH was reported to play a significant role in the development of diabetic retinopathy by elevating retinal mitochondrial superoxide levels." (PMID 35458596, 2022). "Higher levels of GAPDH are found in diabetic retinopathy; in fact, we can see the nuclear translocation of GAPDH in retinal ganglion cells." (PMID 36362243, 2022). "Redox-induced PTMs of GAPDH were reported in several studies on diabetic retinopathy, a disease resulting from chronic hyperglycemia." (PMID 33339386, 2020). "Hyperglycemic conditions were shown to induce nuclear translocation of GAPDH and consequent apoptosis of human retinal Müller and pericyte cells, both of which undergo cell death in diabetic retinopathy." (PMID 33339386, 2020). "The ability of nitrosylated GAPDH to induce apoptosis also plays a significant role in diabetic retinopathy." (PMID 32370188, 2020). "GAPDH performs a significant role in the development of diabetic retinopathy and its progression." (PMID 36836125, 2023). "GAPDH is also critical to the development of diabetic complications, and changes in its nuclear accumulation might aggravate diabetic retinopathy." (PMID 22028962, 2012). "Previous studies have identified several candidate genes associated with the progression of diabetic retinopathy; examples of such candidate genes that were selected in our studies and found to be associated with diabetic retinopathy are GRB2, GHRHR, BMP2, and GAPDH." (PMID 36360284, 2022). "Similarly, high glucose concentrations accumulated GAPDH in the nucleus of bovine retinal endothelial cells, where it could contribute to the progression of diabetic retinopathy." (PMID 22028962, 2012).